HIF1A (hypoxia inducible factor 1 subunit alpha)
Diseases named in the same sentence as HIF1A in open-access papers (continued):
Sharing a sentence is not in itself a finding about the gene and the disease.
tumor (continued). "Because of its inhibitory effect on HIF-1α, which is critical for tumor angiogenesis in a hypoxic microenvironment, YC-1 could be a potential candidate as a hypoxia-targeted agent." (PMID 37749603, 2023). "Furthermore, HIF-1a transcription factor stabilization is the main characteristic of cancer cells under normal oxygen levels, which promotes tumor development and progressionin an oxygen-independent manner." (PMID 36833401, 2023). "Many ubiquitinases act as tumor suppressors by degrading HIF-1α." (PMID 37190313, 2023). "Our study showed that SHMT2decreased tumor cell survival by affecting HIF1α expression, which, in turn, altered the downstream VEGF–STAT3 pathway.Concerning how SHMT2 affected HIF1α, we identified SHMT2’s enzymatic and non-enzymatic roles as contributing to its effect." (PMID 37108312, 2023). "Furthermore, in a UV radiation-induced skin cancer model, an HIF-1α knockout in the epidermis reduced tumor formation and the oncogenic transformation of keratinocytes." (PMID 36901857, 2023). "It causes tumor inflammation through macrophages and increases the expression of TNF-a and IL-6, and also increases angiogenesis with high expression of CD31, VEGFR2, and HIF1a." (PMID 37361568, 2023). "In cancer, hypoxia-inducible factor-1α (HIF-1α) mediates effects such as metabolic shift, production of reactive oxygen species, inhibition of fatty acid β-oxidation, and alteration in the expression of tumor suppressor genes promote tumor progression." (PMID 37367058, 2023). "HIF-2α is considered an oncogene in ccRCC, whereas HIF1α likely has a tumour-suppressive function." (PMID 38136342, 2023). "Treatment with 26G and 36M inhibited HIF-1α expression and interfered with tumor angiogenesis." (PMID 37372967, 2023). "Additionally, it inhibited tumor neovascularization through down-regulation of the HIF-1α-VEGF pathway and facilitated immune checkpoint inhibition by down-regulating PD-1 and PD-L1 expression in tumor tissues." (PMID 37397393, 2023). "HIF-1α can enhance the expression of many cancer stem cell phenotype markers as well as the epithelial cell adhesion molecule EpCAM, which can have increased expression during tumour cell growth and metastasis." (PMID 36879003, 2023). "HIF1A has been showed to regulate the migration of some cells in tumor tissues." (PMID 37237021, 2023). "Moreover, CPT reduced the hypoxia-responsive HIF-1α expression and normalized the tumor vasculature, which help to overcome the hypoxia-induced drug resistance in PDT combination therapy." (PMID 37497002, 2023). "Studies have confirmed that hypoxia-inducible factor 1α (HIF-1α) may reduce tumor control by inducing hypoxia." (PMID 37251681, 2023). "This tumour‐promoting metabolic switch mediates by transforming growth factor signalling, activating HIF‐1α‐transcription, oncogene activation or tumour suppressor gene loss and maintaining tumour cell survival and development in the harsh tumour microenvironment." (PMID 37060186, 2023). "It is also the result of high expression of HIF-1α in tumor cells." (PMID 37384288, 2023). "In the case of hypoxia in the tumor microenvironment, HIF-1α protein, the master regulator of tumorigenesis and mitochondrial respiration, cannot be recognized and degraded, leading to infinite proliferation of tumor cells." (PMID 37899463, 2023). "However, the clinical correlation between HIF-1α and tumor prognosis and progression in OSCC remains controversial." (PMID 37095487, 2023).
tumor (continued). "Interestingly, CRC cell migration and invasion were also promoted by angiogenesis-supporting transcription factor ‘hypoxia-inducible factor’ (HIF)-1α, which is, in turn, initiated by the inflammatory NF-κB-activated milieu in a tumor microenvironment (TME)." (PMID 37583906, 2023). "The tumor suppressor VHL targets HIF1α and HIF2α earmarked for proteasomal degradation." (PMID 36728187, 2023). "Furthermore, due to elevated oncogenic signaling in tumor cells, HIF‐1α expression can also be regulated in an oxygen‐independent manner, including effects on its mRNA transcription and translation." (PMID 36537608, 2023). "In our study, HIF-1α did not correlate with hypoxia, nor with tumor location, nor mutational status." (PMID 37958373, 2023). "Although CA IX expression is almost exclusively induced by the transcription factor HIF-1α during tumor hypoxia, hypoxia is not exclusively associated with cancer." (PMID 36901756, 2023). "HIF-1α activates the expression of pro-angiogenic factors, leading to hypoxia-induced angiogenesis to provide sufficient oxygen, blood supply, and nutrients for tumor growth." (PMID 37107299, 2023). "As previously reported, tumor-infiltrating NK cell activity could be raised by HIF-1α inhibition, suggesting that hypoxia may act directly on NK cells to modulate their immune activity." (PMID 38035113, 2023). "Moreover, IL-6 increased hypoxia-inducible factor 1α (HIF1α) expression and induced tumor immunosuppression by enhancing glucose uptake by cancer cells and competing for glucose with immune cells." (PMID 36764954, 2023). "Additionally, activation of HIF‐1α in a hypoxic tumor microenvironment would affect the metabolism, angiogenesis, and survival of tumor cells and contribute to the development of EMT." (PMID 37102261, 2023). "UCA1 promotes glycolysis by inhibiting the action of mRNA125a, which usually functions as a tumor suppressor but also appears to be involved in blocking HK-II, which in turn could participate in the stabilization of HIF1-α." (PMID 37520325, 2023). "Treatment of HIF-1α has been shown to be effective in CTCL in a xenograft tumor mouse model." (PMID 36761972, 2023). "Inhibitors of glycolysis-related genes, such as PDK1 and LDHA, located downstream of HIF-1α, could decelerate tumor growth." (PMID 37008055, 2023). "Therefore, single-cell genomics and spatial transcriptomics analysis in tumor specimens would allow a thorough exploration of intra-tumoral heterogeneity in HIF-1α and target genes." (PMID 36846589, 2023). "Hif1a transcript levels were significantly higher in T-ALL cells in both organs, implicating hypoxia as a potential mechanism underlying elevated ICAM-1 and VCAM-1 levels in tumor-associated myeloid cells." (PMID 37805579, 2023). "In addition, lactate supports tumor growth through HIF-1α activation and resultant TAMs polarization toward the pro-tumoral M2 phenotype." (PMID 36901858, 2023). "The double HIF-1α and HIPK2 knockout greatly counteracted the tumor growth caused by the HIPK2 knockout, suggesting that the effect of HIPK2 depletion on HCC progression was mediated by HIF-1α and by the HIF-1-induced angiogenesis, further strengthening the effect of the HIPK2/HIF-1α balance." (PMID 36900356, 2023). "Tumor size, macrophage infiltration and HIF-1α, VEGF and P-Akt increased with irradiance." (PMID 36722207, 2023). "Meanwhile, the results of in vitro experiments further showed that LW6 (HIF-1α inhibitor) could effectively inhibit tumor metastasis by inhibiting the expressions of HIF-1α, MMP9, N-cadherin, and Vimentin." (PMID 37239383, 2023). "Moreover, the protein expression levels of VHL and HIF‐1α in tumor tissues collected from xenograft tumor models were detected by IHC, and the results were similar to those from western blotting." (PMID 37563971, 2023). "Similarly, they induced the upregulation of HIF-1α, VEGFα, and SOX2 genes associated with tumor vascularization and tumor cell proliferation, migration, and invasion." (PMID 38013688, 2023).
tumor (continued). "Furthermore, the identification of HIF-1α-mediated transcriptional regulation of ENO2 adds a crucial layer to our understanding of the metabolic adaptations crucial for tumor growth in the context of ccRCC." (PMID 37760940, 2023). "Meanwhile, HIF-1a stimulates autophagy and promotes tumor survival under oxygen deprivation." (PMID 36833401, 2023). "Previous studies have shown that tumor‐infiltrating immune cell‐associated long non‐coding RNA (lncRNAs) are also implicated in cancer immunity regulation and the lncRNA IGFL2‐AS1 can mediate the inhibition of HIF‐1α degradation thus increase CA9 expression." (PMID 37194413, 2023). "Taken together, these data suggest that AEP-specific cleavage of DDX3X leads to nuclear translocation and that nuclear tDDX3X-C regulates oncogenic splicing in multiple kinds of malignant tumors, especially via PRDM2 and ARRB1, under tumor microenvironmental stimuli dependent on HIF1A." (PMID 37988165, 2023). "Nuclear staining of tumor cells for HIF-1α was considered positive." (PMID 38053655, 2023). "On the contrary, low HIF-1α levels in tumor margins and high expression in the tumor were associated with a low risk profile, with no cases of carcinoma recurrence or disease-related death." (PMID 37445908, 2023). "As expected, IH increased HIF-1α gene expression as well as VEGF secretion by tumor cells." (PMID 37108039, 2023). "HIF‐1α protein level was higher in tumor tissue than in normal tissue." (PMID 36971046, 2023). "Moreover, in line with the finding that HIF1A is overexpressed in BRAF-like tumour samples, BRAF-mutated cells display increased levels of HIF1A compared to Nthy-ori 3-1 cells." (PMID 37198319, 2023). "In the context of cancer, HIF-1α may be a master transcriptional factor controlling cellular and developmental processes in response to the metabolic phenotype of the tumor cell." (PMID 36614196, 2023). "Tumor hypoxia stabilizes HIF1α which induces hypoxia-responsive genes including VEGF." (PMID 37577519, 2023). "In light of hypoxia-inducible factor-1α (HIF-1α’s) significant contributions in tumor microenvironment, in solid cancers like HNSCC, targeting and correcting hypoxia may be crucial to enhancing therapeutic response." (PMID 36607847, 2023). "Our data found that DOKD may suppress tumor development via adjusted metastasis and invasive through p-SRc/HIF-1α/Erk1/2/Snail and MMP9 signaling pathways." (PMID 37239383, 2023). "Considering FUS–circTBC1D14 SG formation, we assumed that circTBC1D14 might contribute to its tumor progression function through the granules under hypoxic conditions, among which HIF‐1α is an essential element." (PMID 36806670, 2023). "Neither these authors did find any association between HIF-1α tumor expression and clinicopathological tumor characteristics." (PMID 38273861, 2023). "Interestingly, lactate, uptaken by cells, can inhibit the enzyme prolylhydroxylase 2 (PHD2), leading to HIF-1α activation, angiogenesis and tumor growth." (PMID 37370686, 2023). "Selective targeting of tumor-proximal subsets, potentially combined with HIF-1α inhibition and immune stimulation, may offer a multi-modal therapeutic approach for this disease." (PMID 37350578, 2023). "Quantitative analysis of HIF-1α showed higher levels in Res + Cis, Cis + HT, and Res + Cis +HT groups, indicating increased cell death by apoptosis or necrosis, which is in good agreement with the reduced tumour volume and increased animal survival." (PMID 37446252, 2023). "Furthermore, it is well documented that the tumor core in high grade supratentorial gliomas have a hypoxic core and over-expression and stabilization of hypoxia inducible factor-1 (HIF-1α)." (PMID 37752585, 2023). "A recent study in an autochthonous mouse model of PDAC with pancreas-specific expression of KrasG12D implicates HIF-1α may have a protective role, as genetic deletion of the gene promotes neoplasia." (PMID 37187740, 2023).
tumor (continued). "HIF1α is stabilized with high ROS levels and provides advantage to tumor cells in division." (PMID 36809279, 2023). "Our findings suggest that GSTZ1 may serve as an important tumor suppressor owing to its ability to inhibit the HIF-1α/VEGFA axis in HCC." (PMID 37906252, 2023). "In addition, HIF-1α has been reported to have multiple binding sites for NF-κB p65, highlighting the nature of this link in tumor cells, and our results point out this close relationship between both the transcription factors in promoting CRC cell migration." (PMID 37583906, 2023). "The HIF-1α gene is translated into the HIF-1α protein, which is allied with the stimulation of a series of genes that may worsen the tumor state." (PMID 36983571, 2023). "In the hypoxic tumor microenvironment, HIF-1α can upregulate PD-L1 expression." (PMID 37240068, 2023). "Hypoxia-inducible factor 1-alpha (HIF-1α) activation can upregulate the expression of the natural cytotoxicity receptor NKp44 receptors to reverse impairment in NK cell survival, proliferation, and tumor cytotoxicity." (PMID 36792722, 2023). "Under hypoxic conditions, tumor immune escape involves HIF-1α overexpression." (PMID 37492478, 2023). "In the majority (69%) of cases, the levels of HIF-1α were higher in the kidney than in the tumor." (PMID 38273861, 2023). "Importantly, the present work noticed that hypoxia in the tumor microenvironment facilitates the downregulation of GATA6-AS1 expression in PDAC cells in a HIF1A or HIF2A-independent manner." (PMID 38057853, 2023). "HIF-1α controls the transcription of multiple target genes and participates in many important biological processes, including glycolysis, angiogenesis, invasion and metastasis, tumor stem cell enrichment, immune escape, and so on." (PMID 37904441, 2023). "Tumoral angiogenesis is significantly influenced by HIF-1α, VEGF, and TF." (PMID 37663266, 2023). "Moreover, we stained HIF-1α, PD-L1, and circPRDM4 in the tumor tissues of clinical samples and animal experiments." (PMID 36747292, 2023). "The current study is also the first to reveal the metabolic and anti-tumor immunity roles of miR-22 in the liver; miR-22 targeted both hepatocytes and T cells by silencing HIF1α and increasing RA signaling, both of which have metabolic and anti-inflammatory effects." (PMID 37143325, 2023). "In contrast with this report, we documented that PYGL expression was induced by hypoxia a HIF1α-dependent manner as evidenced by siRNAs targeting HIF1α and luciferase reporter assay, which may due to the different tumor context." (PMID 37063425, 2023). "An enhanced expression of HIF-1α in the metastatic compared to the primary tumours was observed." (PMID 37174052, 2023). "Besides, ESM1 and HIF-1α harbored synergistic functions in tumor angiogenesis and cell proliferation of CSCC cells via the VEGFα/VEGFR2/ERK signaling pathway based on in vitro experiments." (PMID 37476182, 2023). "In conclusion, the present study suggested that miR-873-5p may act as a tumor suppressor in GBM progression by downregulating the HMOX1/HIF1α/SPOP signaling axis." (PMID 37382594, 2023). "The time-dependent and dosage-specific effects of sorafenib on tumor invasion may be due to differences in the regulation pattern of the effect of IL-6 on HIF-1α, namely, positive regulation in the early stage and negative regulation in the later stage." (PMID 37476196, 2023). "Hypoxia-inducible factor-1α (HIF-1α), a key transcriptional factor in tumor microenvironment, could boost miR-182 expression by directly binding to its promoter, thus favoring exosomal secretion." (PMID 38062424, 2023). "A few decades later, a study employing a xenograft model of human non-small cell lung cancer further demonstrated substantial differences between X-ray and C-ion radiation; the latter induced a ninefold reduction in HIF-1α levels and significantly delayed tumor growth." (PMID 37760464, 2023).
tumor (continued). "We reviewed the possible mechanisms through which HIF-1α/ERRα regulates the expression of metabolism-related genes and various signaling pathways in malignant tumors, thereby regulating the energy metabolism of tumor cells and resistance to pyroptosis." (PMID 37864196, 2023). "Furthermore, the tumor amount of HIF-1α in Group 1 was significantly lower compared to Group 2 [p (t) < 0.0001 (14.74)]." (PMID 38273861, 2023). "Meanwhile, the results of in vitro experiments further showed that LW6 could effectively inhibit tumor angiogenesis by inhibiting the expressions of HIF-1α and VEGFA." (PMID 37239383, 2023). "Additionally, NO, produced by endothelial nitric oxide synthase (eNOS), can be activated by various stimuli, including HIF-1α, and also promotes tumor angiogenesis by inducing endothelial cell growth, migration, and tube formation." (PMID 37400960, 2023). "Hypoxia is one of most typical features in the tumor microenvironment of solid tumor and an inducer of endoplasmic reticulum (ER) stress, and HIF-1α functions as a key transcription factor regulator to promote tumor angiogenesis in the adaptive response to hypoxia." (PMID 37752569, 2023). "Therefore, we investigated the effects of CA on HCT-116 CRC cells in a 3D-TME in vitro cultivation, focusing on a possible functional link between the tumor-promoting transcription factors NF-κB and HIF-1α." (PMID 37583906, 2023). "As a result, HIF-1α protein expression is stabilized and promotes tumor growth and angiogenesis." (PMID 37444583, 2023). "The balance between BMAL1 and Hif-1α affects the metabolism of macrophages and anti-tumor immunity." (PMID 36647780, 2023). "This metabolic reprogramming is partly induced via the hypoxia-inducible factor 1 alpha (HIF1α) pathway, which supports the shift towards glycolysis but also plays a role in several other key factors of tumor progression, e.g., invasion and metastasis, genomic instability and pH homeostasis." (PMID 36982873, 2023). "Specifically, tumor-derived EVs produced in the hypoxic microenvironment of tumor cells can polarize macrophages to the M2 phenotype in a HIF-1α- or HIF-2α-dependent manner, which facilitates the establishment of an immunosuppressive microenvironment, thus contributing to PMN formation." (PMID 38037077, 2023). "In agreement with this, parental or lines generated by culturing KD PML tumors expressed higher levels of HIF1a protein and its target, VEGFa that may account for a higher tumor angiogenic activity." (PMID 37518985, 2023). "As a result, HIF-1α becomes stable and activates genes responsible for tumor cell growth survival." (PMID 36891273, 2023). "HIF-1α is known to upregulate Vegfa to promote tumor angiogenesis." (PMID 37965321, 2023). "In addition, Snai2 is activated by HIF1α under hypoxia in the tumor microenvironment to promote metastasis." (PMID 37377752, 2023). "Interestingly, for the used treatment temperatures, the intracellular HIF-1α accumulation in tumor cells seems to play a role in MAPK/ERK activation and mediator secretion (e.g., VEGF, PDGF-AA, Angiopoietin-2), as shown by inhibition experiments." (PMID 37626752, 2023). "Various tumor cells were also reported to express angiogenesis factors under the hypoxic condition to favor tumor progression, such as IL-6, MMPs, VEGF and hypoxia-inducible factor (HIF)-1α, and IL-37 treatment was proven to prevent tumor cells from producing such factors." (PMID 37928545, 2023). "Moreover, HIF-1α mRNA levels were significantly increased in OSCC tumor tissues from patients with metastasis, indicating a positive correlation between HIF-1α expression and OSCC metastasis." (PMID 37095487, 2023). "Next, we have analyzed whether the genetic status (genotype for rs2057482/rs11549465 in HIF1A) influences HIF-1α expression in either normal or tumor tissue." (PMID 38273861, 2023). "Mitochondrial dysfunction impairs hypoxia-induced expression of HIF-1α and delays tumor growth." (PMID 37108616, 2023).